BCL2 (BCL2 apoptosis regulator)
Diseases named in the same sentence as BCL2 in open-access papers (continued):
Sharing a sentence is not in itself a finding about the gene and the disease.
lung carcinoma (continued). "H1299 cells are exactly the lung cancer cells that express high levels of endogenous Mcl-1 but do not express Bcl-2." (PMID 31956373, 2020). "The results show that ABN-B inhibited the proliferation of four human lung cancer cell lines (A549, BZR, H1975, and H226) and induced apoptosis, based on the cleavage of caspase-7 and PARP (poly (ADP-ribose) polymerase), as well as the downregulation of Bcl-2." (PMID 33327489, 2020). "Therefore, the spliceosome is a major actor of cell survival in lung cancer and also define RNF113A as a promising anti-cancer target to fight the acquired resistance to BCL-2 inhibitors." (PMID 32152280, 2020). "Moreover, it stimulated cell proliferation and increased total antioxidant capacity of A549 cells and triggered BCL2/BAX-mediated apoptosis, as well as necrosis and mitotic catastrophe, and inhibited the migratory potential of A-549 lung cancer cells." (PMID 31089377, 2019). "Anti-apoptotic BCL-2 family proteins (BCL-2, BCL-xL, and MCL-1) are emerging as important factors for drug resistance in lung cancer and may represent new targets for treatment." (PMID 31150457, 2019). "This points to an important role of Bcl-2 in our model cell line and in fact abnormal expression of Bcl-2 has been reported in lung cancer than in adjacent non-cancerous tissues and Bcl-2 is discussed as a prognostic factor." (PMID 29927992, 2018). "The anti-cancer effect of econazole in lung cancer cells may be attributable to the induction of apoptosis via the down-regulation of p-AKT and Bcl-2." (PMID 29269744, 2017). "Conversely, up-regulation of Bcl2 was confirmed in human lung cancer tissue samples, inversely correlated with miR-206 expression and validated miR-206 binding sites are present within the 3′-untranslated region (3′-UTR) of Bcl2." (PMID 27821806, 2017). "Western blotting results also indicated that the Bax/Bcl2 ratio, cleaved-caspase 3/9 were increased and the expression levels of VEGF were decreased in tumors, indicating that apoptosis of H1299 lung cancer cells results from regulation of the intrinsic pathway." (PMID 28686182, 2017). "In another study, CAP-induced ROS disturbed the mitochondrial-nuclear network in the A549 lung cancer cell through a caspase-independent apoptotic pathway by downregulating the anti-apoptotic protein Bcl2, but by no activation of caspase 3/732." (PMID 27445062, 2016). "ING5 overexpression up-regulated the expression of pro-apoptotic proteins AIF and cytochrome c, and down-regulated the expression of anti-apoptotic proteins Bcl-2, XIAP and survivin, accounting for its apoptosis-induced role in lung cancer cells by mitochondrial pathway." (PMID 27409347, 2016). "• The EGFR kinase inhibitor Erlotinib increased Bim expression in lung cancer cells sensitive to the drug, but not in resistant cells.• Bcl-2 inhibits the cell death induced by erlotinib." (PMID 26405162, 2015). "By promoting Bcl-2 expression, MTDH significantly inhibited lung cancer cell apoptosis." (PMID 26287185, 2015). "In the present study, we found that miR-206 was dramatically down-regulated in lung cancer tissues compared with matched normal lung tissues, and it inhibited the tumorigenic potential of lung cancer cells by down-regulating oncogenic targets, such as MET and Bcl2." (PMID 26325180, 2015).
lung carcinoma (continued). "We demonstrated that Bcl-2 degradation appeared to be involved in apoptosis triggered by GO6976 (an inhibitor specific for PKC α and β) or shRNA-PKC α plus β in Swiss3T3 cells transformed by v-K-ras or murine lung cancer LKR cells harboring oncogenic K-ras." (PMID 26041886, 2015). "The expression level of BCL-2 differs for different cell types; however high levels and aberrant patterns of BCL-2 expression were reported in a wide variety of human cancers, including lung cancer." (PMID 24999473, 2014). "However, reports regarding high bcl-2 expression predicting a good response in HNSCC or lung cancer are conflicting." (PMID 25380690, 2014). "Importantly, nicotine induces Bcl2 phosphorylation through signaling pathways involving activation of PKCα and the MAPKs ERK1 and ERK2 in lung cancer cells." (PMID 24967145, 2014). "In lung cancer, luteolin confirms its ability to interfere with cancer progression and development, by inhibiting migration of NSCLC cells and inducing apoptosis, through the incremented activation of Caspase-3 and Caspase-9, decreased Bcl-2 and increased Bax expressions." (PMID 38203299, 2023). "Lung cancer apoptosis dysregulation may also involve alterations in the expression of BCL-2 family proteins, such as the downregulation of the pro-apoptotic protein BAX and the upregulation of anti-apoptotic proteins such as BCL-2." (PMID 37371940, 2023). "Also, all the tuft cell-like lung cancer subtypes significantly expressed BCL2 and KIT, and tuft cell-like NECs unlike non-tuft cell-like NECs overexpressed MYC." (PMID 36402755, 2022). "Interestingly, previous studies have demonstrated a lack of expression of BCL-2 in A549 human lung carcinoma cells, the parent cells of EA.hy926." (PMID 35805077, 2022). "After transfecting the human IL-22 cDNA into lung cancer A549 and PG cells, the overexpression of IL-22 inhibited the chemotherapy-mediated apoptosis of A549 and PG cells through the activation of STAT3 and its downstream antiapoptotic proteins, such as Bcl-2 and Bcl-xl." (PMID 35669104, 2022). "Moreover, LSM1 was highly correlated with “Chemoresistance pathways mediated by constitutive activation of PI3K pathway and BCL-2 in small cell lung cancer” and “IGF-1 receptor/EGFR cooperation in lung cancer”, which suggested that it also plays an important role in lung cancer tumor growth." (PMID 34638387, 2021). "It was newly discovered that RT could decrease the level of the Bcl-2 protein in primary lung cancer cells, while we did not observe this effect before in the lung cancer cell line H460." (PMID 32260280, 2020). "Consistent with the reports which provided evidence that the mitochondrial depolarization in lung cancer cells was due to the imbalance of Bax/Bcl-2, we found that treatment with PRIS increased the cellular level of proapoptotic Bax and reduced the levels of antiapoptotic Bcl-2." (PMID 32733636, 2020). "Furthermore, PAM-Ap/pMiR-34a NPs was efficient to modulate the expression of B Cell Lymphoma 2 (BCL-2) and p53genes in vitro, inhibiting cell growth, migration, and invasion, and inducing apoptosis of lung cancer cells, compared with non-targeted NPs." (PMID 31861156, 2019). "c-Met, Bcl2 and cyclin D1 are important oncogene that shown strong power of oncogenicity, by promotion of cell growth, migration, invasion and epithelial mesenchymal transition (EMT), as well as inhibition of cell apoptosis in many tumors including lung cancer." (PMID 26325180, 2015).
lung carcinoma (continued). "Second, miR-206 can directly regulate mRNA expression by targeting the 3′-UTR of MET and BCL2, and inhibit protein expression of cyclin D1 and gene expression of cyclin D1, cyclin D2 and matrix metalloproteinase 9 (MMP-9), while increased p57 gene expression in lung cancer cell (A549)." (PMID 26325180, 2015). "To explore the relevance of the signaling pathways we have characterized, in cell lines for clinical patients, the phosphorylation status of Bcl2, Mcl-1, Bad, or Bax in tumor tissues from smoking and nonsmoking lung cancer patients which should be evaluated in future studies." (PMID 24967145, 2014). "Klotho could also inhibit proliferation and increase apoptosis of human lung cancer A549 cells, which may be partly due to the inhibition of IGF-1/insulin pathways and involving regulating the expression of the apoptosis-related genes bax/bcl-2." (PMID 23516476, 2013). "Besides, NT157 decreased expression of oncogenes BCL2, CCND1, MYB, and MYC and increased genes related to cellular stress and apoptosis, JUN, BBC3, CDKN1A, CDKN1B, FOS, and EGR1 (p < 0.05), favoring a tumor-suppressive cell signaling network in the context of lung cancer." (PMID 36224313, 2022). "Our results suggest that Wogonin may induce the apoptosis of lung cancer cells by inhibiting the PIK-3 signaling pathway, inducing the expression of the pro-apoptotic factor Bad and activating cleaved caspase-3, as well as inhibiting the expression of the anti-apoptotic factor Bcl-2." (PMID 34630106, 2021). "Since c-Met is the target protein of an important proto-oncogene MET, Bcl2 plays anti-apoptosis role in vivo and vitro, and cyclin D1 is the key role on regulation of cell cycle regulated by MET, aberrations of these three proteins might contribute to human lung cancer." (PMID 26325180, 2015). "Thus, in addition to Bcl2 and Mcl-1, nicotine- or NNK-induced survival may occur, at least in part through inactivation of the BH3-only molecule Bad by phosphorylation, which may contribute to the development of human lung cancer and/or chemoresistance." (PMID 24967145, 2014). "In summary, klotho, a potential tumor suppressor, can inhibit the growth of lung cancer cells A549 and promote their apoptosis, this may be partly due to the inhibition of IGF-1/insulin pathways and involving regulating the expression of the apoptosis-related genes bax/bcl-2." (PMID 20642846, 2010). "Econazole also specifically decreased the expression levels of Bcl-2 but not MMP-9 or VEGF, suggesting that econazole induces apoptosis in lung cancer cells." (PMID 29269744, 2017). "The expression of the proteins (p-STAT3, Bcl-2 and Survivin) showed no obvious changes when the phosphorylation of STAT3 was inhibited or IL11Rα were silenced in lung cancer cells." (PMID 27922075, 2016). "Activation of Bcl-2 has been reported in prostate CSC studies, but its activation and the regulation by IL-6 signaling in lung cancer CSCs have not been addressed before." (PMID 26675547, 2016). "For example, in the lung cancer brain metastasis model constructed by the human NSCLC PC-9 cell line, Bcl-2 was also significantly upregulated, while Bcl-xl is not remarkably upregulated, suggesting that the expression of apoptosis-related proteins depends on the cancer cell lines." (PMID 35645820, 2022).
lung carcinoma (continued). "BDA-366, a Bcl-2 BH4-selective antagonist, was found to induce conformational changes in the exposure of the BH3 domain and abrogate the anti-apoptotic function of Bcl-2, and further significantly anti-tumor activity without platelet reduction in lung cancer and diffuse large B-cell lymphoma." (PMID 37237269, 2023).
melanoma (528 papers, 2002 to 2026). A malignant, usually aggressive tumor composed of atypical, neoplastic melanocytes. "These associations between UV exposure, COP1, ETS1, BCL2, and melanoma apoptosis can provide new insight into fundamental melanoma pathophysiology, although no precise common mechanism between UVB exposure and decline in ARSB has been identified." (PMID 40562100, 2025). "LNT promoted the interaction between nuclear receptor Nur77 and mitochondrial apoptosis-associated protein Bcl-2, thereby inducing apoptosis in melanoma cells." (PMID 39744474, 2025). "It thus appears quite clear that melanoma cell survival and apoptosis deficiency cannot be overcome by inhibition of just one specific anti-apoptotic Bcl-2 protein; the activity of all of these proteins must be interrupted." (PMID 38542429, 2024). "Expression of genes modulated by Bcl-2 and associated to Hippo pathway were validated in human melanoma, breast adenocarcinoma and non-small cell lung cancer cell lines by qRT-PCR." (PMID 38755629, 2024). "This is the case of BRAF mutations in melanoma cells correlating with enhanced levels of immunosuppressive mediators such as IL-6 and IL-10 or anti-apoptotic Bcl-2 and Bcl-xL proteins, regulating the expression of several interleukins, such as IL-8 and IL-1β." (PMID 36768978, 2023). "Whatever the outcome, our findings are in agreement with evidence demonstrating the importance of NF-kB in melanoma progression, and the relevance of Bcl-2 and Bcl-xL to regulate cancer progression-associated properties through NF-kB." (PMID 37488586, 2023). "As predicted, compounds 1, 2, and 3 downregulated mitochondrial Bcl-2 and upregulated Bax gene expression, thus suggesting a potent induction of mitochondria-associated apoptosis in A375 melanoma cells." (PMID 36077389, 2022). "Knockdown of BCL2 can cause melanoma cells to exhibit increased apoptosis rates upon external stimulation and can improve the efficiency of drug action 41-44." (PMID 33746605, 2021). "MITF induces Bcl-2 expression, reducing tumorigenesis in human melanoma cells and increasing the tyrosinase expression associated with melanogenesis." (PMID 34067095, 2021). "DHODH inactivation inhibits cell proliferation and induces cell cycle arrest at the S phase in BCL-2 (pro-apoptotic) deficient melanoma cells." (PMID 34900699, 2021). "The αvβ3 integrin overexpression in melanoma cells is associated with induction of bcl2 to prevent apoptosis, and matrix metalloproteinase (MMP)-2 to break down the collagen of the basement membrane." (PMID 34067929, 2021). "To assess the relevance of our observation in patients with melanoma, we performed a retrospective analysis by using a collection of 24 metastatic melanoma biopsies, associating the bcl-2 expression with the M2 marker CD163." (PMID 32269145, 2020). "CM derived from bcl-2 overexpressing melanoma cells treated with IL-1β blocking antibody caused a strong inhibition of M2 macrophage polarization, resulting in significant reduction of M2 (CD206, CCL1, CCL22) and induction of M1 (COX-2 and IL-12) markers." (PMID 32269145, 2020). "To assess the involvement of NF-κB in the bcl-2-mediated M2 macrophage polarization, we impaired the nuclear translocation of p65 by transfecting bcl-2 overexpressing melanoma cells with IKBSR, the mutated form of IKBα acting as NF-κB super repressor." (PMID 32269145, 2020). "Our analyses of TCGA data identified higher expression of BCL2 in cutaneous BRAF-WT melanoma, compared to those with a BRAF hotspot mutation." (PMID 32764384, 2020). "In melanoma, the ratio of BAX, a pro-apoptotic protein, and Bcl-2, an anti-apoptotic protein, is considered to be important in relation to the susceptibility of melanoma to apoptosis; thus, these proteins are considered as a therapeutic target." (PMID 32722030, 2020).